KNTC1 (kinetochore associated 1)
Description:
Essential component of the mitotic checkpoint, which prevents cells from prematurely exiting mitosis. Required for the assembly of the dynein-dynactin and MAD1-MAD2 complexes onto kinetochores. Its function related to the spindle assembly machinery is proposed to depend on its association in the mitotic RZZ complex.
Synonyms: Rod; KIAA0166
Tractability: Antibody: its Gene Ontology location is reachable by antibodies, with high confidence. PROTAC: ubiquitination databases record sites on it; its protein half-life has been measured.
Gene: Protein-coding gene on chromosome 12 (122,527,246 to 122,626,396, forward strand). Ensembl gene ENSG00000184445.
Subcellular location: Cytoplasm; Nucleus; Chromosome, centromere, kinetochore; Cytoplasm, cytoskeleton, spindle
Subcellular location (Human Protein Atlas): Cytosol; Plasma membrane
Pathways (Reactome):
Cell Cycle: Amplification of signal from unattached kinetochores via a MAD2 inhibitory signal; EML4 and NUDC in mitotic spindle formation; Mitotic Prometaphase; Resolution of Sister Chromatid Cohesion; Separation of Sister Chromatids
Signal Transduction: RHO GTPases Activate Formins
Gene Ontology:
Molecular function: protein binding; small GTPase binding
Biological process: mitotic spindle assembly checkpoint signaling; mitotic sister chromatid segregation; protein localization to kinetochore involved in kinetochore assembly; protein-containing complex assembly; regulation of attachment of spindle microtubules to kinetochore; regulation of exit from mitosis
Cellular component: cytosol; kinetochore microtubule; RZZ complex; spindle pole; cytoplasm; nucleus; spindle
Genetic constraint (gnomAD): Loss-of-function variants: 95 observed, 134.92 expected, observed/expected ratio (o/e) 0.7, 90% interval 0.6 to 0.83. The upper end of that interval is the gene's LOEUF score, 0.83, which puts it in group 3 of 6, group 1 being the genes least tolerant of losing a copy. Missense variants: 1,257 observed, 1,408.7 expected, observed/expected ratio (o/e) 0.89, 90% interval 0.85 to 0.94. Synonymous variants: 498 observed, 513.35 expected, observed/expected ratio (o/e) 0.97, 90% interval 0.9 to 1.04.
Homologues: Orthologues: chimpanzee KNTC1 (99% identical), macaque KNTC1 (97% identical), pig KNTC1 (89% identical), dog KNTC1 (89% identical), rabbit KNTC1 (88% identical), guinea pig KNTC1 (82% identical), rat Kntc1 (81% identical), mouse Kntc1 (81% identical), tropical clawed frog kntc1 (59% identical), zebrafish kntc1 (45% identical), Drosophila melanogaster rod (19% identical), Caenorhabditis elegans rod-1 (17% identical).
Diseases named in the same sentence as KNTC1 in open-access papers:
KNTC1 is named in the same sentence as 40 diseases in open-access papers, as found by Europe PMC text mining. Sharing a sentence is not in itself a finding about the gene and the disease. The quoted sentences say what the papers report.
pancreatic cancer (7 papers, 2019 to 2023). "Moreover, the high expression of KNTC1 is associated with the poor prognosis of pancreatic cancer patients." (PMID 37280656, 2023). "Thus, high KNTC1 expression was associated with high malignancy and poor prognosis in pancreatic cancer." (PMID 35852618, 2023). "KNTC1 could be linked to the pathophysiology of pancreatic cancer and may be an early diagnostic marker of cervical precancerous lesions." (PMID 35852618, 2023). "This study aimed to explore the role and possible mechanisms of KNTC1 in the development of pancreatic cancer." (PMID 35852618, 2023). "The present study evaluated the relationship between KNTC1 and pancreatic cancer using differential gene and pan-cancer analyses, and analyzed the expression of KNTC1 in pancreatic cancer cell lines." (PMID 35852618, 2023). "According to the western blot analysis, the protein expression level of KNTC1 was also upregulated in pancreatic cancer compared to the para-cancerous samples." (PMID 35852618, 2023). "We investigated the relationship between KNTC1 expression and clinicopathological features of pancreatic cancer." (PMID 35852618, 2023). "We found, by RNA sequencing combined with differential gene analysis, that the expression of KNTC1 was upregulated in pancreatic cancer." (PMID 35852618, 2023). "We found that KNTC1 was upregulated in pancreatic cancer and likely participates in its progression." (PMID 35852618, 2023). "The present study is the first to identify the role of KNTC1 in regulating the growth of pancreatic cancer." (PMID 35852618, 2023). "We found that KNTC1 expression levels were significantly upregulated in the pancreatic cancer cell lines compared to normal human pancreatic ductal epithelial (HPDE) cells." (PMID 35852618, 2023). "In summary, we found that high expression of KNTC1 in pancreatic cancer was related to pathological grade and clinical prognosis." (PMID 35852618, 2023). "With immunohistochemical staining, we found that the high expression of KNTC1 in pancreatic cancer was related to pathological grade and clinical prognosis." (PMID 35852618, 2023). "We determined the expression levels of KNTC1 in three human pancreatic cancer cell lines (BxPC-3, PANC-1, and SW1990)." (PMID 35852618, 2023). "We confirmed the interaction between KNTC1 and cell division cycle associated 8 (CDCA8) by immunoprecipitation, which indicates that KNTC1 interacts with CDCA8 in pancreatic cancer." (PMID 35852618, 2023). "We analyzed differentially expressed genes by RNA sequencing in three paired pancreatic cancer and para-cancerous tissue samples and found that the expression of KNTC1 was significantly upregulated in pancreatic cancer." (PMID 35852618, 2023). "Through immunohistochemical detection of the clinical samples, the expression of KNTC1 in tumor tissues of patients with pancreatic cancer was found to be significantly upregulated and related to pathological grade and overall survival time." (PMID 35852618, 2023). "Finally, genomic enrichment analysis (GSEA) was performed to clarify the role of KNTC1 in pancreatic cancer tumorigenesis and to infer the potential mechanism." (PMID 35852618, 2023). "Similarly, RT-PCR results indicated that the expression of KNTC1 was higher in three groups of pancreatic cancer cell lines (BxPC-3, PANC-1, and SW1990) than in normal pancreatic ductal cells." (PMID 35852618, 2023). "Therefore, knockdown of KNTC1 can inhibit the proliferation of pancreatic cancer cells and block the cell cycle in the G2 phase." (PMID 35852618, 2023). "Similarly, we found that the expression of KNTC1 was higher in three groups of pancreatic cancer cell lines (BxPC-3, PANC-1, and SW1990) than in normal pancreatic ductal cells." (PMID 35852618, 2023). "The expression of KNTC1 was significantly upregulated in pancreatic cancer." (PMID 35852618, 2023). "Knocking down KNTC1 inhibited the growth of pancreatic cancer and promoted apoptosis." (PMID 35852618, 2023).
pancreatic cancer (continued). "Further research determined that the high expression of KNTC1 in pancreatic cancer was related to the pathological grade and clinical prognosis of pancreatic cancer, indicating that the expression of KNTC1 was higher in pancreatic cancers with a higher pathological grade and later stage." (PMID 35852618, 2023). "However, the function of KNTC1 and the key molecular mechanism of pancreatic cancer require further research." (PMID 35852618, 2023). "In addition, bioinformatics results indicated that KNTC1 is a vital gene for the occurrence and development of hepatocellular carcinoma, nasopharyngeal carcinoma, pancreatic cancer, and neuroblastoma, and is related to extracellular matrix reconstruction." (PMID 35389773, 2022). "Several bioinformatics studies have also established that the KNTC1 gene could be one of the vital genes associated with cancer development, including HCC, Pancreatic cancer (PC), and nasopharyngeal carcinoma (NPC)." (PMID 33616161, 2021). "However, little is understood of the function of KNTC1 in pancreatic cancer." (PMID 35852618, 2023). "However, to the best of our knowledge, no previous reports have described the significance of KNTC1 in pancreatic cancer, and the specific molecular mechanisms involved remain obscure." (PMID 35852618, 2023).
cervical cancer (6 papers, 2021 to 2024). A primary or metastatic malignant neoplasm involving the cervix. "Meanwhile, the cervical cancer tissue with a lower level of EREG just harbored higher mutative frequencies of KNTC1 and RTL1." (PMID 37020674, 2023). "Moreover, relevant bioinformatics publications demonstrated that KNTC1 was associated with a poor outcome in patients with hepatocellular carcinoma and cervical cancer." (PMID 35354488, 2022). "In this study, we hypothesized that KNTC1 promotes the development of cervical cancer, and explored the underlying mechanism by cell culture and animal experiments." (PMID 35389773, 2022). "Studies have shown that KNTC1 can promote the invasion and progression of cervical cancer, hepatocellular carcinoma, and non-small-cell lung cancer." (PMID 37280656, 2023). "In this study, we verified the important role of KNTC1 in cervical cancer using bioinformatics analysis." (PMID 35389773, 2022). "Based on cell and animal experiments, we concluded that KNTC1 can enhance the invasion, migration, and tumorigenicity of tumor cells via MMP2 and MMP9, providing a basis for the subsequent study of KNTC1 as a target for cervical cancer treatment." (PMID 35389773, 2022). "To validate the results of bioinformatics analysis, we first determined KNTC1 expression in normal human cervical epithelial cells, HcerEpic, and in two cervical cancer cell lines, SiHa and C-33A." (PMID 35389773, 2022). "After confirming the increased expression of KNTC1 in cervical cancer cell lines, we needed to clarify the role of KNTC1 in cervical cancer." (PMID 35389773, 2022). "We used wound healing and Transwell assays to analyze the role of KNTC1 in migration and invasion of cervical cancer cells." (PMID 35389773, 2022). "Wound healing experiments showed that cervical cancer cells with low KNTC1 expression had a slower wound healing rate than the shCtrl group." (PMID 35389773, 2022). "This suggested that KNTC1 knockdown reduces the migration and invasion abilities of cervical cancer cells." (PMID 35389773, 2022). "Bioinformatics analyses have shown remarkable expression of KNTC1 in cervical cancer tissues, which has been confirmed by immunohistochemistry; moreover, KNTC1 has been reported to be elevated in the blood of patients with cervical cancer." (PMID 35389773, 2022). "KNTC1 is a highly potent candidate for becoming a therapeutic target for cervical neoplasms in future, and has vital implications in cervical cancer therapy." (PMID 35389773, 2022). "Tissue microarray analysis shows that the expression of KNTC1 in vivo is higher in high-grade squamous intraepithelial lesions than in normal cervix, and KNTC1 is a novel tumor suppressor that can prevent the occurrence and development of cervical cancer." (PMID 38693472, 2024). "In this study, we initially explored the role of KNTC1 in cervical cancer." (PMID 35389773, 2022). "In this study, we hypothesized and verified that KNTC1 participates as an oncogene in the development of cervical cancer." (PMID 35389773, 2022). "KNTC1 promotes the proliferation of cervical cancer cells in vitro." (PMID 35389773, 2022). "Further, we verified the promotional effect of KNTC1 on cervical cancer through in-vivo and in-vitro experiments and speculated that KNTC1 might mediate tumor invasion via MMP9 and MMP2." (PMID 35389773, 2022). "Taken together, our study showed that KNTC1 plays an important role in cervical cancer." (PMID 35389773, 2022). "We found that, compared to that in HcerEpic, a type of normal cervical epithelial cell, KNTC1 was overexpressed in cervical neoplasia cell lines C-33A and SiHa, suggesting that KNTC1 may be upregulated in cervical cancer, which was consistent with previous bioinformatics results." (PMID 35389773, 2022). "After combining the heat map results, we chose KNTC1 as the follow-up research focus, since its main function involved cell cycle and DNA replication, and it has not been studied in cervical cancer." (PMID 35389773, 2022).
esophageal squamous cell carcinoma (6 papers, 2021 to 2023). Esophageal squamous cell carcinoma (ESCC) is a type of esophageal carcinoma (EC) that can affect any part of the esophagus, but is usually located in the upper or middle third. "A recent study indicated that silencing KNTC1 with shRNA inhibited cell viability and caused apoptosis in esophageal squamous cell carcinoma." (PMID 35354488, 2022). "In addition, it is reported that KNTC1 is associated with esophageal squamous cell carcinoma." (PMID 37480569, 2023). "It has been reported that MCM4 and CENPI are involved in mediating chromosomal stability to influence the cell cycle and that KNTC1 knockdown suppresses cell viability and induces apoptosis in esophageal squamous cell carcinoma." (PMID 36035209, 2022). "Similar to our study, KNTC1 knockdown in esophageal squamous cell carcinoma, colon cancer, and bladder cancer had resulted in decreased cell viability and slower proliferation." (PMID 35389773, 2022). "In addition, KNTC1 was reported to correlate with esophageal squamous cell carcinoma, and downregulation of KNTC1 expression inhibited cell viability and induced cell apoptosis in ESCC cell lines." (PMID 35933405, 2022).
hepatocellular carcinoma (6 papers, 2022 to 2024). A malignant tumor that arises from hepatocytes. "It was shown that Kntc1 was highly expressed in hepatocellular carcinoma (HCC) tissues and was associated with poor prognosis, suggesting a key role for Kntc1 in HCC development." (PMID 38971916, 2024). "Published literature showed that KNTC1 was widely expressed in hepatocellular carcinoma tissues and was related to poor prognosis." (PMID 35933405, 2022). "The literature shows that KNTC1 may affect the biological activity of hepatocellular carcinoma cells through PI3K/Akt signal pathway, and high KNTC1 expression is associated with the poor prognosis." (PMID 37480569, 2023).
colorectal cancer (4 papers, 2009 to 2025). A primary or metastatic malignant neoplasm that affects the colon or rectum. "Prathapan Thiru had found that KNTC1 is upregulated in colorectal cancer, liver cancer, bladder cancer, breast cancer, and other tumors, and is coordinately expressed with other kinetochore proteins, as suggested by comparative datasets." (PMID 35389773, 2022). "Also in colorectal cancer tissues, KNTC1 is largely highly expressed and correlates with pathological grading of the disease and overall survival." (PMID 38134110, 2023). "The role of KNTC1 in human cancers is not well documented, however, a single report describes mutation in this gene in colorectal carcinoma." (PMID 19664251, 2009). "KIF14, KIF18B, KIF23, KIF4A, KNTC1, NCAPG2, and MCM3 regulate chromosomal integrity, mitotic spindle formation, and DNA replication, processes that are frequently dysregulated in colorectal cancer." (PMID 40405535, 2025).
neuroblastoma (4 papers, 2010 to 2025). Neuroblastoma (NB) is the most common solid, extracranial childhood tumor. "Also, compared with the healthy control group, the KNTC1 expression in neuroblastoma samples increased statistically." (PMID 33616161, 2021). "Furthermore, the Kntc1 needle-shaped structure was observed in different cell types, such as mouse primary neurons, HypoN-E1 hypothalamus-derived cells and Neuro2a neuroblastoma cells, indicating that glutamine-dependent localisation of Kntc1 is a general issue." (PMID 39829138, 2025). "Using the in silico data mining approach, we identified elevated expression of five genes located at the 12q24.31 amplicon in neuroblastoma (DIABLO, ZCCHC8, RSRC2, KNTC1 and MPHOSPH9)." (PMID 20444257, 2010). "In addition to DIABLO, also ZCCHC8, RSRC2, KNTC1 and MPHOSPH9 showed statistically increased expression in neuroblastoma samples when compared to the groups of healthy samples." (PMID 20444257, 2010).
non-small cell lung carcinoma (4 papers, 2022 to 2025). A group of at least three distinct histological types of lung cancer, including non-small cell squamous cell carcinoma, adenocarcinoma, and large cell carcinoma. "KNTC1 can be used as a tumor promoter in the occurrence and development of non-small cell lung cancer by colony formation, cell migration and inhibiting apoptosis." (PMID 37480569, 2023). "It is worth noting that KNTC1 may regulate non-small cell lung cancer through its downstream target PSMB8." (PMID 37480569, 2023).
bladder cancer (2 papers, 2022 to 2026). "In bladder cancer, KNTC1 knockdown has been reported to reduce tumor cell migration." (PMID 35389773, 2022).
breast carcinoma (2 papers, 2022). "The biological functions of KNTC1 were still unclear in breast cancer." (PMID 36233194, 2022). "In conclusion, the current study showed that CCNE2, CDCA5, RAD51, TCF19, KNTC1, MCM10, and NEIL3 might contribute to EPT-related tumorigenesis in breast cancer, with CCNE2 might be a sensitive risk indicator of breast cancer risk in women using MHT." (PMID 36233194, 2022).
liver cancer (2 papers, 2022 to 2025). An epithelial or non-epithelial malignant neoplasm that arises from the liver. "KNTC1 knockdown inhibits the proliferation and metastases of liver cancer." (PMID 40282296, 2025).
lung carcinoma (2 papers, 2020 to 2022). "Furthermore, AURKB, CCNB2, CDC20, CDCA5, CDCA8, CENPF, and KNTC1 are were highly expressed in lung cancer tissues and were associated with poor prognosis." (PMID 35598017, 2022).
oral squamous cell carcinoma (2 papers, 2021 to 2022). "They found that KNTC1 expression was related to tumor size in oral squamous cell carcinoma; compared to small tumors, larger tumors had a lower expression level." (PMID 35389773, 2022). "Previous studies have shown that the KNTC1 transcriptional activity changes with the size of tumor in patients with oral squamous cell carcinoma." (PMID 33616161, 2021).
cholangiocarcinoma (1 paper, 2025). A carcinoma that arises from the intrahepatic biliary tree (intrahepatic cholangiocarcinoma) or from the junction, or adjacent to the junction, of the right and left hepatic ducts (hilar cholangiocarcinoma). "For example, distinct peptide mass fingerprints (PMFs) were identified for early versus late recurrence in cholangiocarcinoma (CCA), where peptides such as KNTC1, DCLK1, ALG10, ATR, and BLM were associated with early recurrence, while SERPINA1, TGFB2, and SERPING1 were implicated in late recurrence." (PMID 41008874, 2025).
gallbladder carcinoma (1 paper, 2023). "Similarly, we also found that KNTC1 gene is highly expressed in gallbladder cancer, higher the KNTC1, worse the prognosis." (PMID 37480569, 2023). "Gene expression heat map showed that KNTC1, MCM2, CKAP2, RACGAP1, CCNB1 were highly expressed in gallbladder carcinoma samples." (PMID 37480569, 2023). "The main result of this study is that KNTC1 and MCM2 genes are highly expressed in gallbladder carcinoma." (PMID 37480569, 2023). "We found that five core genes (KNTC1, MCM2, CKAP2, RACGAP1, CCNB1) were highly expressed in gallbladder carcinoma samples and low in normal samples." (PMID 37480569, 2023). "KNTC1 and MCM2 may be molecular targets for early diagnosis and precise treatment of gallbladder cancer, and provide a basis for the study of the mechanism of gallbladder cancer." (PMID 37480569, 2023). "The public datasets were used to validate roles of KNTC1 and MCM2 in gallbladder cancer." (PMID 37480569, 2023). "However, relationship between KNTC1 and MCM2 and gallbladder cancer is unclear." (PMID 37480569, 2023). "However, the relationship between KNTC1, MCM2 genes and gallbladder cancer is not clear." (PMID 37480569, 2023).